CD4 (CD4 molecule)
Diseases named in the same sentence as CD4 in open-access papers (continued):
Sharing a sentence is not in itself a finding about the gene and the disease.
Burkitt lymphoma (22 papers, 2009 to 2025). A rare form of malignant mature B-cell non-Hodgkin lymphoma. "Burkitt lymphoma (BL), which has been increasing in recent years, typically presents with type I latent infection and develops after CD4 recovery with cART treatment." (PMID 40733522, 2025). "In summary, we present an HIV patient with low CD4 counts who presented with localized pain and intestinal obstruction and was diagnosed with Burkitt lymphoma of the bone, lymph nodes, duodenum, stomach, pancreas, and small intestine." (PMID 36620831, 2022). "Using a co-culture system where ALCL (DEL, SU-DHL-1), cHL (L-428, L-1236) or Burkitt lymphoma (Ramos) cell lines were cultured together with CD4+ T cells isolated from peripheral blood, we studied rosette formation capacity in vitro." (PMID 31581676, 2019). "While the defects in HLA class I-mediated Ag presentation by Burkitt lymphoma (BL) have been well documented, CD4+ T-cells are also poorly stimulated by HLA class II Ag presentation, and the reasons underlying this defect(s) have not yet been fully resolved." (PMID 22162713, 2011). "Furthermore, cocultures of NLRP11-expressing Burkitt's lymphoma cells and naïve human peripheral CD4+ T lymphocytes had reduced IFN-γ and IL-17A production, whereas IL-13 and IL-10 cytokines did not change." (PMID 32832566, 2020). "Immune dysregulation in people with HIV, even those with higher CD4 counts, could potentiate a weaker immune response to Epstein–Barr virus-positive Burkitt lymphoma that remains asymptomatic for longer, leading to greater mortality risk and a more advanced stage at diagnosis." (PMID 38611075, 2024). "MMP19 was highly expressed in adipocytes, heart, liver, and Burkitt’s lymphoma cells (Raji cells), and PLXDC1 was highly expressed in CD4+ T cells, CD56+ NK cells, CD8+ T cells, thymus cells and pineal cells." (PMID 39118664, 2024). "Due to the low expression of MHC class-II molecule on the targeted cell, a murine Burkitt lymphoma cell line B6SJ003, the splenocytes cultured with OT-II peptide were selected using anti-CD4 beads prior to the cytotoxicity assay." (PMID 23145026, 2012). "However, in HIV-positive individuals, immune surveillance is compromised due to reduced CD4 + T cell counts, allowing unchecked EBV replication and B-cell transformation, which increases the likelihood of oncogenesis and Burkitt lymphoma development." (PMID 41180747, 2025). "Moreover, lytic activity of EBNA1-specific CD4+ T cells against virus-transformed tumor cells was observed in all EBV-mediated malignancies, including Burkitt lymphoma (BL)." (PMID 37965314, 2023). "The NCDB does not include data about CD4 counts, HIV viral load, or individual drug regimens that constitute chemotherapy and immunotherapy regimens for Burkitt lymphoma." (PMID 38611075, 2024). "Based on limited data, Burkitt lymphoma is not common, which is surprising since Burkitt lymphoma occurs in PHA with relatively high CD4 count." (PMID 19327166, 2009). "On day 1 after the addition of T cells, we observed that cHL cell lines formed clusters with CD4+ T cells more efficiently than ALCL cell lines, whereas almost no clusters were formed in the negative control co-cultured with the Burkitt lymphoma cell line Ramos." (PMID 31581676, 2019).
chronic hepatitis (22 papers, 2007 to 2025). An active inflammatory process affecting the liver for more than six months. "Acute and chronic hepatitis caused by hepatitis E virus and acute liver failure are also caused by the infiltration of CD4+ T cells and CD8+ T cells." (PMID 34434948, 2021). "In contrast, TIM-3, ICOS, and 4-1BB-positive CD8+ T cells as well as PD-1, TIM-3, and 4-1BB-positive CD4+ T cells were enriched mainly in the liver of chronic hepatitis patients." (PMID 39882238, 2024). "Data expressed as the frequency of the cells per the lymphocyte population revealed a significantly increased frequency of PD-1+CD4+ T and 4-1BB+CD4+ T cells in the chronic hepatitis group compared to the control liver." (PMID 39882238, 2024). "Activation of CD4+ T cells, CD8+ T cells, NK cells, NKT cells, monocytes/macrophages, and HSCs occurs in chronic hepatitis caused by HBV." (PMID 36281288, 2022). "In human HBV hepatitis, there are more IL-21-producing CD4+ T cells in acute hepatitis than in chronic hepatitis, and the number is positively correlated with the number of HBV-specific CD8+ T cells." (PMID 34502427, 2021). "The CD4+ T-cell response in patients who recovered was found to be more frequent, stronger, and more multispecific than that observed later in patients with chronic hepatitis." (PMID 25215259, 2014). "In multivariate analysis, no statistical significant associations were observed between either development of toxicity or treatment discontinuation and gender, chronic hepatitis, age or CD4-cell count at BSL or at switch (all p>0.05)." (PMID 25397538, 2014). "Similar to the CD8+ T cells, CD4+ T cells have also been found to exhibit a lower response in the acute phase of infection in patients who developed chronic hepatitis later." (PMID 25215259, 2014). "Chronic hepatitis in HIV infection has also been associated with poor HIV-specific treatment outcomes, such as current CD4+ T-lymphocyte counts < 200 cells/mm3 and detectable HIV-1 RNA levels." (PMID 23885958, 2013). "We observed marked enrichment of CD161+CD4+ T cells in the liver during chronic hepatitis such that they are the dominant subtype (mean 55% of CD4+ T cells)." (PMID 23181064, 2012). "CD4 T-cells likely play a more crucial role in maintaining the prolonged activation of CD8 T-cells observed in chronic hepatitis and in the formation of memory CD8 T-cells." (PMID 21779338, 2011). "However, with the transition to chronic hepatitis, exhaustion of CD4+ T cells is as prominent as the exhaustion of CD8+ T cells." (PMID 34502427, 2021). "Our observations support the conclusion that hepatic n-3 PUFAs could influence the differentiation of CD4+ T cells into various effector subsets in the liver during immune-mediated hepatitis, and therefore modulate the pathogenesis of autoimmune and chronic hepatitis." (PMID 27679638, 2016). "Our results revealed an accumulation of intrahepatic CD4+ T cells expressing TIM-3 and 4-1BB in the chronic hepatitis group compared to the control liver." (PMID 39882238, 2024). "Using IHC analysis of lymphocyte subsets in liver tissue infiltration and distribution, a study found that patients with ACLF had increased intrahepatic CD4+ T cells, CD8+ T cells, and NK cells compared with the chronic hepatitis and normal control group." (PMID 34434948, 2021). "Similarly, with the HLA-DR1 tetramer we found maintained levels of tetramer+ CD4+ T cells in three spontaneously recovered patients, one of whom had cleared HCV more than 20 years before, but only low frequencies in patients with chronic hepatitis." (PMID 17653276, 2007). "This exhausted phenotype and the lack of CD4 T-cell help may contribute to the persistence of virus in chronic hepatitis." (PMID 21779338, 2011).
demyelinating disease (22 papers, 2012 to 2025). A broad group of disorders that affect the myelin sheaths that cover the neurons. "OCA-B expressing CD4+ T cells display pathogenic stem-like properties and preferentially transfer demyelinating disease." (PMID 40299553, 2025). "In contrast, studies have indicated that Th17 CD4+ T cells are associated with the pathogenesis of TMEV-induced demyelinating disease." (PMID 32727036, 2020). "Taken together, these results demonstrate that PLP-CD8 employ an ordered regulatory program over a number of days in vivo to suppress pathogenic PLP-specific CD4 T cell responses and inhibit demyelinating disease." (PMID 30356717, 2018). "B cell–targeting therapies for demyelinating disease may therefore reduce the repertoire of pathogenic CD4 T cells by decreasing T cell epitope diversity." (PMID 39330967, 2024). "Overall, in the classic TMEV induced biphasic MS models, it remains unclear whether Th2 cytokines play a protective (suppression of pathogenic CD4 Th1 cells) or pathogenic role (by increasing antibody production) in demyelinating disease." (PMID 22348089, 2012). "Thus, the potential function of virus-specific FoxP3+CD4+ T cells accumulated in the CNS of susceptible mice early after TMEV infection may contribute to the pathogenesis of TMEV-induced demyelinating disease." (PMID 33086489, 2020). "The effects of preimmunization and tolerization with individual epitopes indicate that capsid-specific CD4+ T cells are protective, whereas viral RNA polymerase (3D21–36)-specific CD4+ T cells exacerbate the development of TMEV-induced demyelinating disease." (PMID 34067536, 2021). "The results indicate that the presence of activated virus-specific CD4+ T cells protects the mice from the development of TMEV-induced demyelinating disease, whereas naive virus-specific CD4+ T cells promote the pathogenesis." (PMID 33086489, 2020). "Our results in this study indicate that the presence of a high level of initial virus-reactive CD4+ T cells exacerbates the development of TMEV-induced demyelinating disease." (PMID 33086489, 2020). "It has been well established that the pathogenesis of this virus-induced demyelinating disease is immune-mediated, with the primary involvement of Th1 type CD4+ cells." (PMID 32727036, 2020). "Our results demonstrate that preexisting naive VP2-specific CD4+ T cells promote the pathogenesis of TMEV-induced demyelinating disease at high initial viral loads, but VP2-primed VP2-specific CD4+ T cells protect against the pathogenesis." (PMID 33086489, 2020). "Taken together, results in this study suggest that the balance between the initial viral load and virus-specific CD4+ T cells plays a critical role in the development of TMEV-induced demyelinating disease." (PMID 33086489, 2020). "Together, these data indicate that PLP-CD8 suppress PLP-specific CD4 T cell responses in vivo during demyelinating disease." (PMID 30356717, 2018). "Uncovering those IL-16-specific mechanisms is critical for the development of new CD4+ T cell subset-targeted therapies for MS and other chronic and/or progressive inflammatory and demyelinating diseases." (PMID 25896927, 2015). "Depletion of the CD11b+Ly-6C+ cells via administration of an anti-GR-1 Ab resulted in reduced development of demyelinating disease and enhanced virus-specific CD4+ and CD8+ T cell responses." (PMID 25250029, 2014). "CD4+ Tregs are thought to play a major role in the macrophage-mediated inhibition of demyelinating disease." (PMID 23805274, 2013). "CD25loFoxP3+CD4+ T cells do not display a regulatory function, and the presence of a high level of CD25loFoxP3+CD4+ T cells may promote the development of TMEV-induced demyelinating disease." (PMID 37153539, 2023). "However, the contribution of anti-TMEV antibodies to the protection of mice from demyelinating disease is relatively minor compared with the protection by CD4+ Th1 and CD8+ T cells." (PMID 37153539, 2023).
demyelinating disease (continued). "Therefore, the levels of initial viral load and virus-reactive CD4+ T cells play critical roles in their expansion and differentiation leading to the protection or pathogenesis of virus-induced demyelinating disease." (PMID 33086489, 2020). "Thus, the initial viral dose and the frequency of virus-specific CD4+ T cells appear to be critically important in the development of clinical demyelinating disease." (PMID 33086489, 2020). "Delineating molecular mechanisms enhancing migration of encephalitogenic CD4+ cells (Th1 and Th17), and Treg cells into the CNS throughout the disease, is essential in the development of new therapy specific for CD4+ T cell subsets for MS and similar inflammatory and demyelinating diseases." (PMID 25896927, 2015). "Additionally, TMEV-infected, anti-GR-1 Ab-treated mice had decreased myelin-specific CD4+ T cell responses compared to control Ab-treated mice during the demyelinating disease at a later time post-infection." (PMID 25250029, 2014). "As virus-reactive IFN-γ-producing Th1 cells are protective but IL-17-producing Th17 cells inhibit Th1 development and cytotoxic T cell function, FoxP3+CD4+ T cells together with Th17 cells may promote the pathogenesis of TMEV-induced demyelinating disease in an epitope-dependent manner." (PMID 34067536, 2021). "However, the relationship between the levels of initial viral load, virus-specific CD4+ T cells, and the pathogenesis of demyelinating disease remains unknown." (PMID 33086489, 2020). "However, under a low viral load, the preexisting naive virus-specific CD4+ T cells are protective, indicating that a balance between the levels of initial viral loads and virus-reactive CD4+ T cells plays a critical role in the pathogenesis of TMEV-induced demyelinating disease." (PMID 33086489, 2020). "Interestingly, as the recovered mice age, they develop a secondary lethal progressive demyelinating disease starting around 40 weeks after tamoxifen injection that is mediated by MOG35–55-specific CD4+ T cell infiltration into the CNS during the late stages of disease." (PMID 33192332, 2020). "Previous studies have indicated that the level of CD4+ T cells plays an important role in the protection and/or pathogenesis of TMEV-induced demyelinating disease." (PMID 33086489, 2020). "The T cells we identified in our human postmortem tissue were of both CD4 and CD8 origin, similar to what can be observed in PD and more classically, demyelinating disorders such as MS." (PMID 31993745, 2020). "Here, we show that PLP-CD8 swiftly ameliorated ongoing demyelinating disease and rapidly suppressed PLP-specific CD4 T cell responses by employing a temporally distinct cytokine effector program over a number of days in vivo." (PMID 30356717, 2018). "Antibodies to viral determinants appear to play a minor role in the protection of mice from the pathogenesis of demyelinating disease compared with CD4+ T cells and CD8+ T cells." (PMID 32727036, 2020). "Given that CD4 T cells from EAE mice are sufficient to transfer disease to healthy animals, the field has focused for many years on this encephalitogenic cell, its Th1 and Th17 pro-inflammatory states, and its role in driving demyelinating disease." (PMID 30356717, 2018). "Given that PLP-CD8 altered the trajectory of ongoing demyelinating disease progression within just 2 days of treatment, we hypothesized that PLP-CD8 could rapidly suppress PLP-specific CD4 T cell responses in vivo." (PMID 30356717, 2018). "However, antibodies to viral determinants appear to play a relatively minor role in the protection of mice from the pathogenesis of demyelinating disease compared to CD4+ Th1 and CD8+ T cells." (PMID 34067536, 2021).
demyelinating disease (continued). "Because TMEV is a neurotropic virus, and the cytokine environment plays a key role in the differentiation of T cells, the sites of the initial CD4+ T cell amplification and differentiation may be critically important in the pathogenesis of TMEV-induced demyelinating disease." (PMID 33086489, 2020). "Because virus-reactive IFN-γ-producing Th1 cells are protective, but IL-17-producing Th17 cells are known to inhibit Th1 development and cytotoxic T cell functions, FoxP3+CD4+ T cells, together with Th17 cells, may promote the pathogenesis of TMEV-induced demyelinating disease." (PMID 33086489, 2020). "We have now demonstrated that in the wild-type setting, unlike their CD4 counterparts, CNS-CD8 not only fail to transfer or exacerbate demyelinating disease, but are unexpectedly protective against EAE." (PMID 30356717, 2018).
diphtheria (22 papers, 2009 to 2025). A Gram-positive bacterial infection caused by Corynebacterium diphtheriae. "In case of diphtheria toxoid, univariate analysis showed significant associations of humoral response with CD4, unswitched memory B cells, dendritic cells (mDC and pDC) and monocyte frequencies, however, multivariate analysis revealed a strong association with pDC only." (PMID 33968011, 2021). "To evaluate the significance of Tregs for CLL progression we used DEREG transgenic mice with depletion of FoxP3+ CD4+ Tregs by treatment with diphtheria toxin (DT)." (PMID 35296093, 2022). "Mice which had received all three shots of Infanrix® IPV and were sacrificed 7 days after the third shot had significantly more diphtheria-specific CD4+ T cells producing IL-2, IL-6, or TNF-α when treated with GM-CSF than placebo-treated controls." (PMID 29961602, 2018). "In a recent study we found a positive correlation between diphtheria-specific granulocyte macrophage-colony stimulating factor (GM-CSF) production by CD4+ T cells, and peripheral diphtheria-specific antibodies in adults." (PMID 29961602, 2018). "We identified negative correlations between CD4+CD28null T cells and humoral responses to a tetanus-diphtheria vaccine (TIV), together with day 7 PC/B expansions." (PMID 33728434, 2021). "Interestingly, plasma concentrations of diphtheria-specific antibodies negatively correlated with highly differentiated CD8+CD57+ T cells as well as with exhausted central memory CD8+ and CD4+ T cells in the BM." (PMID 31462901, 2019). "A low co-expression between CTLA-4 and LIR-1 was observed on CD4+ IFN-γ+ T cells in response either to the parasite lysate (median percentage ± SD = 10±11, range = 2.1–37) or to diphtheria toxoids (median percentage ± SD = 2.9±5.4, range = 0.7–12)." (PMID 22574131, 2012). "Negative correlations were seen between diphtheria-specific antibody concentrations and highly differentiated CD8+CD57+ T cells, exhausted PD-1+ CM CD8+ T cells, and PD-1+ CM CD4+ T cells in the BM." (PMID 31462901, 2019).